SRSF2 (serine and arginine rich splicing factor 2)
Diseases named in the same sentence as SRSF2 in open-access papers (continued):
Sharing a sentence is not in itself a finding about the gene and the disease.
pancreatic cancers (3 papers, 2012 to 2022). "Upregulation of SRSF1 and SRSF2 proteins has been shown in a large variety of carcinoma, including renal, breast, ovarian, cervical, colon and pancreatic cancers." (PMID 23071587, 2012). "A two-stage case-control study was conducted to examine the association between six candidate U2-depedent spliceosome genes (SRSF1, SRSF2, SF3A1, SF3B1, SF1 and PRPF40B) and pancreatic cancer (PC)." (PMID 26498691, 2015).
primary myelofibrosis (3 papers, 2016 to 2022). Myelofibrosis with myeloid metaplasia is a myeloproliferative disease with annual incidence of approximately 1 case per 100,000 individuals and age at diagnosis around 60 (an increased prevalence is noted in Ashkenazi Jews). "Thirteen genes including ASXL1, U2AF1, SRSF2, SF3B1, and ZRSR2 had significantly higher mutation frequencies in primary myelofibrosis (PMF) compared with essential thrombocythemia and polycythemia vera; this difference distinguished PMF from MPN and likened it to MDS." (PMID 33117717, 2020). "Gene mutations in epigenetic regulators (ASXL1, TET2, DNMT3A and EZH2) and RNA splicing (U2AF1 and SRSF2) were considered as the additional subclonal mutations and cooperated with the MPN driver mutation (JAK2, MPL or CALR) to play a key role in the pathogenesis of primary myelofibrosis." (PMID 35740649, 2022).
systemic mastocytosis (3 papers, 2021 to 2025). Systemic mastocytosis (SM) comprises a heterogeneous group of rare acquired and chronic hematological malignancies that are related to an abnormal proliferation of mast cells in tissue, including bone marrow, with or without skin involvement. "Midostaurin treatment in systemic mastocytosis patients has shown that patients with one or more mutations in the S/A/R (SRSF2, ASXL, or RUNX1) panel have a lower survival rate and a higher progression rate to AML or mast cell leukemia than patients without mutations." (PMID 38007419, 2023). "Other somatic gene alterations implicated in some cases of advanced systemic mastocytosis include mutations in TET2, SRSF2, ASXL1, RUNX1, CBL, JAK2, NRAS, and KRAS." (PMID 41440762, 2025). "Interestingly, NGS analysis did not detect any mutations in all the other KIT exons analyzed nor in other genes previously reported in patients with advanced systemic mastocytosis (TET2, SRSF2, ASXL1, RUNX1, CBL, JAK2, NRAS, and KRAS)." (PMID 41440762, 2025).
acute liver failure (2 papers, 2022). Rapid deterioration of liver function causing encephalopathy and coagulopathy. "In an animal model with liver-specific SRSF2 depletion, acute liver failure with elevated oxidative stress was also observed, indicating the importance of alternative splicing in cellular redox homeostasis and survival." (PMID 35326115, 2022).
ischemic stroke (2 papers, 2022 to 2025). A stroke disorder caused by obstruction of blood flow to the brain, due to thrombotic (local blood clot formation) or embolic (due to a blood clot or other material traveling from another site) event. "For example, we showed that SRSF2, a spliceosome mutation, is significantly associated with better ischemic stroke outcomes and lower risk of ICH." (PMID 40093911, 2025).
liver failure (2 papers, 2017 to 2019). A liver disease characterized by the liver losing or has lost all of its function. "The importance of a properly functioning SRSF2 protein can be seen in vivo where SRSF2 was silenced in mouse hepatocytes, leading to liver failure and death, while injection of SRSF2-silenced HCC cells into mice resulted in an inability to form tumors." (PMID 31162605, 2019). "Like the Srsf2 knockout, loss of Srsf3 causes endoplasmic reticulum stress, hepatocyte apoptosis and proliferation, and liver damage but did not cause the liver failure seen in the Srsf2 knockout." (PMID 28680417, 2017).
lung squamous cell carcinoma (2 papers, 2012 to 2017). "Here, we demonstrate that not only SRSF1 but also SRSF2, SRPK1 and SRPK2 proteins are overexpressed in both adenocarcinoma and squamous cell lung carcinoma." (PMID 23071587, 2012).
osteosarcoma (2 papers, 2022 to 2023). A usually aggressive malignant bone-forming mesenchymal neoplasm, predominantly affecting adolescents and young adults. "It shows that the expression of ACSL3 was not correlated with the expression of BRD4 and SRPK2, but positively correlated with SRSF2, which is consistent with our findings in 10 cancerous tissues surgically removed from patients with osteosarcoma." (PMID 37993451, 2023). "In order to determine which lncRNA was involved in osteosarcoma, lncRNAs including lnc-SELPLG-2:1, lnc-DDX47–3:1, lnc-ZNF77–165:3, lnc-SRSF2–9:2, lnc-SAMD11–1:1, and lnc-PPP1R9B-4:2 were detected by RT-qPCR to determine if their sequences were consistent with sequencing results." (PMID 36199080, 2022). "Finally, 18 paired osteosarcoma tissues and normal osteogenic tissues were selected from the GEO database (cancerous tissue matched 1:1 with adjacent osteogenic tissue, GSE99671) to analyze the expression correlation between BRD4, SRPK2, SRSF2 and ACSL3." (PMID 37993451, 2023).
poliovirus infection (2 papers, 2011 to 2015). An disease or disorder caused by infection with Enterovirus C. "For example, nuclear-resident proteins fibrillarin, TATA-box-binding-protein 1 (TBP1), and serine/arginine-rich splicing factor 2 (SRSF2 or SC35) do not relocalize from the nucleus to the cytoplasm during poliovirus infection." (PMID 26150805, 2015).
renal cell carcinoma (2 papers, 2024 to 2025). "So far, it has been demonstrated that expression of serine/arginine-rich splicing factor 2 (SRSF2) in renal cell carcinoma patients (RCC) is involved in the regulation of IC expression (inter alia BTLA), which in turn modulates TILs’ exhaustion." (PMID 38233898, 2024).
spinal muscular atrophy (2 papers, 2022 to 2024). A motor neuron disease that affect the muscles, and characterized by muscle weakness and atrophy resulting from progressive degeneration and irreversible loss of the anterior horn cells in the spinal cord (i.e., lower motor neurons) and the brain stem nuclei. "SRSF2 is involved in spinal muscular atrophy and altered splicing of survival motor neuron exon 7, which negatively affects splicing." (PMID 38042508, 2024). "Recent studies further indicated an involvement of SRSF2 in regulating mRNA alternative splicing and expression of SMN, a key protein in inherited spinal muscular atrophy (SMA)." (PMID 35326115, 2022).
squamous cell carcinoma (2 papers, 2012 to 2020). A carcinoma arising from squamous epithelial cells. "In this study, we investigated the status of SRSF1, SRSF2 and its phosphorylated form P-SRSF2, as well as of SRPK1 and SRPK2 in a series of 107 NSCLC, including 54 adenocarcinoma (ADC) and 53 squamous cell carcinoma (SCC)." (PMID 23071587, 2012). "Subsequently, it was shown that S385 DNp63a phosphorylation is induced by cisplatin in squamous cell carcinoma cells, leading to RNA splicing and ACIN1-mediated cell death via interaction with spliceosome components SAP18, RBM38, ELAVL, SRPK2, SRSF2, and ACIN1." (PMID 33375680, 2020).
VEXAS syndrome (2 papers, 2024 to 2025). An adult-onset inflammatory disease that affects only males and is caused by somatic, not germline, mutations. "Whereas in VEXAS syndrome, UBA1 mutations alone are thought to drive both the inflammatory and MDS phenotypes, in UBA1‐wildtype patients with MDS/CMML, early somatic mutations in TET2/IDH1 (and/or SRSF2) are thought to contribute to the MDS/CMML and SIAD components." (PMID 39981058, 2024).
viral infection (2 papers, 2021 to 2022). "Increasing evidence has demonstrated that SRSF2 and other SR proteins are associated with the progression of a variety of diseases, including viral infection and tumorigenesis." (PMID 33994855, 2021). "SRSF2 has been shown to be involved in the alternative splicing of many target pre-mRNAs that are associated with human diseases, including viral infection, tumors, and neurodegenerative diseases." (PMID 33994855, 2021). "SRSF2 (serine and arginine rich splicing factor 2; also known as SFRS2) gene plays vital roles in a number of biological and pathological processes and it is associated in humans with the progression of a variety of diseases, including viral infection and tumorigenesis." (PMID 35581286, 2022). "In addition to genes related to virus infection and tumor progression, SRSF2 has been shown to mediate the pre-mRNA splicing of multiple neurodegenerative disease-related genes." (PMID 33994855, 2021).
autoimmune disease (1 paper, 2022). A disorder resulting from loss of function or tissue destruction of an organ or multiple organs, arising from humoral or cellular immune responses of the individual to their own tissue constituents. "Various molecular abnormalities like TET2, SRSF2, ASXL1, and RAS are reported in the pathogenesis of CMML, but no such mutations have been described to explain the strong association of autoimmune diseases and severe inflammatory phenotype seen in CMML." (PMID 35281324, 2022).
breast tumors (1 paper, 2016). "Analysis by immunohistochemistry of the expression of hnRNP A1, hnRNPH, RBM9/FOX2, SRSF1/ASF/SF2, SRSF2/SC35, SRSF3/SRp20, SRSF7/9G8 in breast tumors shows that the expression of hnRNP A1, but not the other tested RBPs, is associated with metastatic relapse." (PMID 26930004, 2016).
cardiac conduction diseases (1 paper, 2018). "Indeed, disruptions to the TBX5/SRSF2 equilibrium result in Holt-Oram Syndrome, which include cardiac conduction diseases such as AF that can occur alone or in combination with atrial and ventricular septal defects." (PMID 29848314, 2018).
cervical cancer (1 paper, 2022). A primary or metastatic malignant neoplasm involving the cervix. "Another SR protein SRSF2 has been shown to be required for E6E7 mRNA production only in cervical cancer-derived cells." (PMID 35832386, 2022). "The knock-down of SRSF2 in cervical tumor cells results in cell apoptosis, suggesting its oncogenic role in cervical cancer progression." (PMID 35832386, 2022).
COVID-19 (1 paper, 2022). A disease caused by infection with severe acute respiratory syndrome coronavirus 2. "Additionally, both TET2 and SRSF2, genes involved in pre-mRNA splicing, are associated with systemic inflammatory and autoimmune disease (SIAD), an umbrella term that includes ulcerative colitis and infectious diseases, such as COVID-19." (PMID 35228982, 2022).
dilated cardiomyopathy (1 paper, 2018). Cardiomyopathy which is characterized by dilation and contractile dysfunction of the left and right ventricles. "SRSF2 dynamics are highly regulated in cardiac tissue, as cardiac-specific ablation of SRSF2 results in dilated cardiomyopathy and abnormal Ca2+ handling linked to down-regulation of the cardiac specific ryanodine receptor." (PMID 29848314, 2018).
hereditary neutrophilia (1 paper, 2017). A leukocyte disease characterized by autosomal dominant inheritance of lifelong, persistent elevated neutrophil counts primarily consisting of segmented neutrophils that has material basis in heterozygous mutation in the CSF3R gene on chromosome 1p34. "By contrast, CSF3R P733T mutations detected in CMML patients were completely different from CSF3R mutation types described in patients with CNL, SCN and hereditary neutrophilia, which may be a potential diagnostic marker, particularly for wt SRSF2 CMML patients." (PMID 28209919, 2017).
hypertrophic cardiomyopathies (1 paper, 2019). "Finally, while conditional cardiac Srsf1 knockout animals die postnatally from defective juvenile-to-adult heart remodeling, conditional cardiac knockouts of Srsf2 (SC35) and Srsf4 (Srp75) are viable but develop dilated and hypertrophic cardiomyopathies, respectively." (PMID 31791406, 2019).
Hypoglycemia (1 paper, 2021). A decreased concentration of glucose in the blood. "Loss of SRSF2 also decreased expression of metabolic genes such Ebp, Baat, Slc27a5, resulting in hypoglycemia indicating an essential role of SRSF2 in hepatic metabolism." (PMID 33716968, 2021).
Infertility (1 paper, 2023). "Male germ cell-specific deletion of Srsf2 by Stra8-Cre caused complete infertility and defective spermatogenesis." (PMID 37867192, 2023). "Here, by crossing Srsf2Floxed/Floxed (Srsf2F/F) mice with Stra8-Cre mice to generate mutant mice with specific deletion of the Srsf2 gene in male germ cells, we found that the SRSF2 knockout caused complete infertility and germ cells were drastically lost during spermatogenesis." (PMID 37867192, 2023).
intracerebral hemorrhage (1 paper, 2025). A cerebrovascular disorder characterized by bleeding into one or both cerebral hemispheres including the basal ganglia and the cerebral cortex. "While the presence of any CH mutation is associated with intracerebral hemorrhage (ICH) (OR = 1.21, P = 0.02), specific mutations, SRSF2 and ASXL1 are protective against ICH (OR = 0.9, P = 0.04) and nontraumatic subarachnoid hemorrhage (OR = 0.92, P = 0.03), respectively." (PMID 40093911, 2025).
male infertility (1 paper, 2023). The inability of the male to effect fertilization of an ovum after a specified period of unprotected intercourse. "These abnormally expressed genes, such as Stra8, Stag3, Atr and Dazl, caused by SRSF2 deletion finally result in the failure of spermatogenesis and male infertility." (PMID 37867192, 2023).
mental disorder (1 paper, 2022). A disease that has its basis in the disruption of mental process. "Eight genes are implicated in viral (SEC14L1, JMJD6, SRSF2, TMPRSS2, MX1, MX2) or bacterial (COL8A1, SPIRE1) infections, seven genes (MFSD11, METTL23, CTTNBP2, BACE2, IMPA2, MPPE1 and GNAL) are involved in mental disorders and one gene (MGAT5B) is related to the Golgi complex." (PMID 35581286, 2022).
nasopharyngeal carcinoma (1 paper, 2020). A carcinoma arising from the nasopharyngeal epithelium. "MiR-20a-5p reduces the sensitivity of nasopharyngeal carcinoma cells to radiotherapy by targeting NPAS2 and Rab27B, and miR-193a-3p enhances the anti-radiation ability of NPC by targeting SRSF2 43-45." (PMID 32328201, 2020).
neuropathies (1 paper, 2021). "Overexpression of DYRK1A was associated with increased phosphorylation of SRSF2 (SC35) and dysregulated alternative splicing of Tau pre-mRNA, confirming the role of this kinase in the production of Tau splice variants associated with Tat-mediated neuropathies." (PMID 33854493, 2021).
neutropenia (1 paper, 2022). A decrease in the number of neutrophils found in the blood. "Finally, 68% of the tested cases displayed at least one somatic mutation, most commonly SF3B1, TET2, ASXL1, and SRSF2, associated with older age, presence of neutropenia, and lower response to ESAs." (PMID 35392224, 2022).
Obesity (1 paper, 2019). Accumulation of substantial excess body fat. "Another priority is to study whether SRSF2 and MBD2_v2 play a role in malignant transformation of partly transformed or noncancerous breast epithelial cells and whether this too may be induced by obesity." (PMID 30636104, 2019).
proteinopathies (1 paper, 2021). "As we observed high-molecular-weight species of dephosphorylated SRSF2 in vitro, we hypothesized that inhibiting SR protein kinases within cells would induce an increase in cytoplasmic granules and/or the formation of fibril-like species, hallmarks of various RBP proteinopathies." (PMID 34673031, 2021).
renal tumours (1 paper, 2016). "The analysis of immunohistochemical (IHC) data revealed that, in renal tumours, SRSF2 staining intensity was reduced by 33.3% (p = 0.0027) when compared with normal kidney tissues." (PMID 27690003, 2016).
respiratory failure (1 paper, 2024). The significant impairment of gas exchange within the lungs resulting in hypoxia, hypercarbia, or both, to the extent that organ tissue perfusion is severely compromised. "Inactivation of Srsf2 in MyoD + progenitors resulted in skeletal muscle dysfunction and respiratory failure." (PMID 39248331, 2024). "In this study, we observed that the absence of Srsf2 in MyoD + progenitors resulted in the perinatal mortality in mice, primarily due to respiratory failure." (PMID 39248331, 2024).
Stroke (1 paper, 2025). Sudden impairment of blood flow to a part of the brain due to occlusion or rupture of an artery to the brain. "Unexpectedly, we found SRSF2, a spliceosome mutation, was associated with favorable functional outcome at 90 days post stroke." (PMID 40093911, 2025).
systemic lupus erythematosus (1 paper, 2020). An autoimmune multi-organ disease typically associated with vasculopathy and autoantibody production. "Additionally, SRSF2 has been associated with a variety of immune disorders including systemic lupus erythematosus (SLE), leukemia, and human immunodeficiency virus infection." (PMID 31838573, 2020).
tauopathies (1 paper, 2014). "As SRSF2 is also increased in PSP patients this suggests mitochondrial complex I inhibition may play at least a partial role in the pathogenesis of 4R tauopathies such as PSP." (PMID 25402454, 2014). "If SRSF2 is confirmed to be a key player in mediating the 4R isoform upregulation in PSP and other 4R tauopathies, this would make it a suitable drug target for reducing this isoform shift." (PMID 25402454, 2014).
Wiskott-Aldrich syndrome (1 paper, 2024). Wiskott-Aldrich syndrome (WAS) is a primary immunodeficiency disease characterized by microthrombocytopenia, eczema, infections and an increased risk for autoimmune manifestations and malignancies. "SRSF2 localization and levels are altered in Wiskott-Aldrich syndrome, a disease that has widespread altered splicing." (PMID 38042508, 2024).